AAMP (angio associated migratory cell protein)
Description:
Plays a role in angiogenesis and cell migration. In smooth muscle cell migration, may act through the RhoA pathway.
Tractability: Antibody: its Gene Ontology location is reachable by antibodies, with high confidence; UniProt places it where antibodies can reach, with medium confidence; the Human Protein Atlas places it where antibodies can reach. PROTAC: ubiquitination databases record sites on it; its protein half-life has been measured.
Gene: Protein-coding gene on chromosome 2 (218,264,125 to 218,270,178, reverse strand). Ensembl gene ENSG00000127837.
Subcellular location: Cell membrane; Cytoplasm
Subcellular location (Human Protein Atlas): Microtubules; Cytokinetic bridge; Cytosol; Plasma membrane; Primary cilium; Primary cilium tip
Pathways (Reactome):
Signal Transduction: Signaling by EGFR; Signaling by VEGF
Hemostasis: Thromboxane signalling through TP receptor
Immune System: NOD1/2 Signaling Pathway
Gene Ontology:
Molecular function: heparin binding; protein binding
Biological process: smooth muscle cell migration; angiogenesis; positive regulation of endothelial cell migration
Cellular component: cell surface; cytosol; plasma membrane; cytoplasm
Genetic constraint (gnomAD): Loss-of-function variants: 12 observed, 52.22 expected, observed/expected ratio (o/e) 0.23, 90% interval 0.15 to 0.37. The upper end of that interval is the gene's LOEUF score, 0.37, which puts it in group 1 of 6, group 1 being the genes least tolerant of losing a copy. Missense variants: 418 observed, 575.3 expected, observed/expected ratio (o/e) 0.73, 90% interval 0.67 to 0.79. Synonymous variants: 210 observed, 227.61 expected, observed/expected ratio (o/e) 0.92, 90% interval 0.82 to 1.03.
Homologues: Orthologues: chimpanzee AAMP (100% identical), macaque AAMP (99% identical), rabbit AAMP (99% identical), dog AAMP (99% identical), guinea pig AAMP (99% identical), mouse Aamp (99% identical), rat Aamp (99% identical), pig AAMP (98% identical), tropical clawed frog aamp (71% identical), zebrafish aamp (58% identical), Drosophila melanogaster CG5114 (31% identical), Caenorhabditis elegans Y111B2A.12 (28% identical). Paralogues in human: NWD2 (24% identical).
Diseases named in the same sentence as AAMP in open-access papers:
AAMP is named in the same sentence as 21 diseases in open-access papers, as found by Europe PMC text mining. Sharing a sentence is not in itself a finding about the gene and the disease. The quoted sentences say what the papers report.
melanoma (3 papers, 2023 to 2024). A malignant, usually aggressive tumor composed of atypical, neoplastic melanocytes. "Angio-associated migratory cell protein (AAMP) was first discovered by Beckner when they screened cell surface proteins related to cell motility in melanoma cells." (PMID 37501187, 2023). "AAMP was originally identified in a human melanoma cell line in a search for proteins crucial to migration but is additionally expressed in various other cell types." (PMID 39404373, 2024). "AAMP, initially isolated from a melanoma cell line, is a pro-tumor protein that contributes to proliferation, angiogenesis, and other biological activities and can be secreted into the extracellular matrix." (PMID 37122729, 2023). "AAMP is expressed in a variety of cell types, including endothelial cells, aortic smooth muscle cells, dermal fibroblasts, renal proximal tubular cells, glomerular mesangial cells, human breast cancer cells, human melanoma cells and prostate cancer cells." (PMID 37501187, 2023).
breast carcinoma (2 papers, 2021 to 2023). "AAMP (angio-associated migratory cell protein) belongs to the immunoglobulin superfamily and has a function in cell migration and angiogenesis in breast cancer and non-small cell lung cancer." (PMID 33428680, 2021). "Furthermore, AAMP is highly expressed in invasive gastrointestinal and breast carcinoma cells and is a marker of poor prognosis." (PMID 37501187, 2023).
glioma (2 papers, 2022 to 2023). A benign or malignant brain and spinal cord tumor that arises from glial cells (astrocytes, oligodendrocytes, ependymal cells). "Since B7-H3 has a role in immune suppression, the expression of AAMP was further examined in glioma cell lines, GICs, immune cell lines, and primary immune cells, which were all positive for this binding partner." (PMID 35919070, 2022). "Angio-associated migratory cell protein (AAMP), ubiquitously expressed in glioma cells, immune cells, and glioma tissue was identified as interaction partner of B7-H3, using bimolecular fluorescence complementation (BiFC) assay, co-immunoprecipitation (co-IP), and functional assays." (PMID 36859240, 2023). "Finally, as B7-H3 expression in glioma is grade-dependent, it was tested whether AAMP is also expressed depending on glioma grade." (PMID 35919070, 2022). "AAMP was ubiquitously expressed in glioma cells, immune cells, and glioma tissue, but did not correlate with glioma grade." (PMID 35919070, 2022).
colon adenocarcinoma (1 paper, 2025). "Notably, AAMP expression was significantly higher in colon adenocarcinoma and rectal adenocarcinoma tissues compared to normal controls." (PMID 40529105, 2025).
ductal carcinoma in situ of the breast (1 paper, 2024). "AAMP is highly expressed in different types of cancer, such as gastrointestinal stromal tumors and ductal carcinoma in situ of the breast with necrosis." (PMID 39404373, 2024).
glioblastoma (1 paper, 2022). The most malignant astrocytic tumor (WHO grade IV). "Prognostic value of angio-associated migratory cell protein (AAMP) and B7-H3 expression was evaluated in isocitrate dehydrogenase 1 wildtype (IDH1wt) glioblastoma (GBM) patients from The Cancer Genome Atlas (TCGA)-GBM cohort." (PMID 35919070, 2022).
liver cancer (1 paper, 2023). An epithelial or non-epithelial malignant neoplasm that arises from the liver. "The immunohistochemical staining also confirmed the increased expression of AAMP in liver cancer." (PMID 37501187, 2023).
renal failure (1 paper, 2019). "Among those peptides showing increased concentrations in renal failure patients, several substances deserve mention: “angio-associated migratory cell protein” (AAMP) plays a role in angiogenesis and cellular adhesion." (PMID 31385015, 2019).
varicocele (1 paper, 2024). A condition characterized by the dilated tortuous veins of the spermatic cord with a marked left-sided predominance. "Whole-exome sequencing in a cohort of patients with varicoceles has identified multiple genetic variants associated with varicoceles (e.g., AAMP, SPINT1, or MK167)." (PMID 38392299, 2024).
cancer (4 papers, 2016 to 2025). A tumor composed of atypical neoplastic, often pleomorphic cells that invade other tissues. "Angio‐associated migratory cell protein (AAMP) is highly expressed in endothelial cells, and recent studies have highlighted its significant role in the initiation and progression of various cancers." (PMID 40529105, 2025). "AAMP was overexpressed in most cancers, and high AAMP expression was associated with worse overall survival (OS), disease-specific survival (DSS), and progress-free interval (PFI) for LIHC and adrenocortical carcinoma (ACC)." (PMID 37501187, 2023). "AAMP or angio-associated migratory cell protein is an element directly associated with angiogenesis and migration of endothelial cells, including cancer cells." (PMID 27598578, 2016). "AAMP regulates angiogenesis, cell migration, and proliferation and is a pro‐cancer factor in some tumor types." (PMID 40529105, 2025). "Previously, it has been shown that AAMP plays a role in cell migration in various cancer cell types, but also in vascular smooth muscle cells and ECs." (PMID 39404373, 2024). "Angio-associated migratory cell protein (AAMP) is a protein that participates in cell migration and is reported to be involved in cancer progression." (PMID 37501187, 2023). "Although the oncogenic role of AAMP has been recognized in several cancers, its function in CRC has not been systematically studied." (PMID 40529105, 2025).
tumor (4 papers, 2022 to 2025). "The later analysis showed expression of both AAMP and B7-H3 in tumor-associated macrophages while lymphocytes expressed mainly AAMP but not B7-H3." (PMID 35919070, 2022). "The results indicate that AAMP expression is significantly higher in CRC tissues compared to normal tissues, and its high expression is closely associated with shortened patient survival and tumor recurrence, suggesting that AAMP may serve as a potential biomarker for CRC." (PMID 40529105, 2025). "Clinical proteomic tumor analysis consortium (CPTAC) proteomic data further confirmed elevated AAMP protein levels in CRC tissues relative to normal tissues." (PMID 40529105, 2025). "Experimentally, downregulating AAMP expression significantly inhibits CRC cell growth and tumor formation, whereas overexpressing AAMP enhances these tumor characteristics." (PMID 40529105, 2025). "In vivo, AAMP knockdown in HT55 cells significantly suppressed tumor growth in a nude mouse xenograft model (p < 0.05)." (PMID 40529105, 2025). "In contrast, AAMP overexpression significantly accelerated tumor growth in xenografts derived from HT55 cells (p < 0.05)." (PMID 40529105, 2025). "We demonstrate in detail the ubiquitous expression of AAMP in the tumor and immune compartment, proving that AAMP is a rational candidate and can explain the immunosuppressive, pro-tumorigenic function of B7-H3." (PMID 35919070, 2022). "Moreover, GP1 displayed increased expression of angiogenic features (e.g., ANGPTL4, EGFR, AAMP) and complement and coagulation cascade components (e.g., C1, C7, C8, C9, PLG, SERPINE1), which have been associated with aggravated tumor invasion." (PMID 35440542, 2022). "AAMP knockdown suppressed CRC cell proliferation, colony formation, and xenograft tumor growth, whereas overexpression exacerbated these phenotypes." (PMID 40529105, 2025). "Furthermore, analysis of CRC tissues at different tumor stages demonstrated a significant correlation between AAMP expression levels and tumor staging (Kruskal–Wallis test, p > 0.05), suggesting that AAMP may be involved in CRC proliferation and malignant progression." (PMID 40529105, 2025).
AAMP also shares sentences with these, for which no sentence is quoted: astrocytoma (1 paper); colon cancer (1); colorectal cancer (1); gastrointestinal stromal tumor (1); gouty arthritis (1); non-small cell lung carcinoma (1); oligodendroglioma (1); prostate carcinoma (1); rectal adenocarcinoma (1); rectal cancer (1).